TSLP (thymic stromal lymphopoietin)
Diseases named in the same sentence as TSLP in open-access papers (continued):
Sharing a sentence is not in itself a finding about the gene and the disease.
allergic disease (continued). "Among Th2-cell subtypes, TNF-α-rich inflammatory Th2 (iTh2) cells may be developed by stimulation of dendritic cells with Th2 adjuvants associated with allergens or thymic stromal lymphopoietin (TSLP) often found in inflammatory tissues in allergic diseases." (PMID 23283296, 2008). "Furthermore, we examined specific SNPs in the TSLP and IL-1β genes to determine their association with the occurrence and number of coexisting allergic diseases, addressing the gaps in understanding the genetic and immunological mechanisms underlying allergic multimorbidity." (PMID 39860604, 2025). "Moreover, disruption of TSLP responses or basophil depletion reduced the susceptibility to intestinal FA, while transfer of TSLP-elicited basophils into intact skin promoted the development of allergic disease." (PMID 37048784, 2023). "Interestingly, epidemiological data suggest an inverse relationship between allergic disease and lung cancer risk, which could be explained by higher serum TSLP levels in the patients." (PMID 35565302, 2022). "Interestingly, here we couldn’t successfully repeat the allergy susceptible loci in TSLP while we identified a signal (rs1438673) in 5q22.1 in WDR36-CAMK4 intergenic region, which are about 50,000 bp far away from TSLP gene." (PMID 32082391, 2020). "In addition, SNPs in the dynamic FAIRE peaks over 200kb upstream of TSLP were also in LD with allergy-associated SNPs suggesting that they may also contain TSLP regulatory elements." (PMID 28953906, 2017). "Because of its key role in triggering inflammation, scientists now view TSLP as a major driver of allergic disease, which is why new targeted treatments are being actively developed." (PMID 40724851, 2025). "RSV-induced trained immunity via TSLP alters immune cell responses and can promote allergic diseases." (PMID 40748050, 2025). "The study findings indicate that children with allergic diseases exhibit higher concentrations of both TSLP and IL-1β compared to healthy controls, supporting the role of the cytokines in promoting and sustaining allergic inflammation." (PMID 39860604, 2025). "They found that the extract suppressed the release of mediators related to skin autoimmunity—IL-6 and IL-17C—and allergy—TSLP (thymic stromal lymphopoietin), IL-6, CCL26 (chemokine (C-C motif) Ligand 26), and MMP-9 (matrix metalloproteinase)." (PMID 40649262, 2025). "TSLP has emerged as a crucial trigger in the onset of allergic diseases, owing to its potent capacity to drive naïve CD4+ T cells toward a Th2-dominant phenotype." (PMID 40724851, 2025). "In recent years, TSLP has garnered extensive attention for its involvement in various disorders, extending beyond its well-known role in allergies." (PMID 40486522, 2025). "Thymic stromal lymphopoietin (TSLP) has garnered significant attention from researchers due to its role in promoting Th2 responses in allergic disease." (PMID 40486522, 2025). "By acting on DCs and promoting the expression of OX40 ligand (OX40L), CD80, and CD86, TSLP promotes allergic reactions by stimulating the differentiation of naive CD4+ T cells into pro-inflammatory TH2 cells that generate IL-4, IL-5, IL-13, and TNF." (PMID 39057040, 2024). "Our pre-clinical study paved the way for future in vivo studies to test the efficacy and the range of anti-TSLP antibody HZ-1127 for allergic diseases and cancer treatment." (PMID 38566968, 2024). "On the other hand, several lines of evidence suggest that TSLP plays a pivotal role in allergic diseases." (PMID 38512921, 2024). "As the key driver in allergic diseases and other types of immune disorders, blocking dysfunctional TSLP activity can be used to treat these diseases." (PMID 39726595, 2024). "The studies summarised in this review indicate that type 2 epithelial cytokines of TSLP and IL‐33 play a role as positive modulators in activation of basophils both directly and also indirectly, leading to exacerbation of allergic reactions." (PMID 39654685, 2024).
allergic disease (continued). "TSLP and IL-33 are two alarmin cytokines that drive type 2 responses at the skin barrier level and hence play a role in the early development of allergic reactions." (PMID 39076967, 2024). "Among the genes and cognate proteins suppressed by the NTCI, was the major driver of allergic reactions, Thymic Stromal Lymphopoietin (TSLP), that promotes Th2 response." (PMID 38846687, 2024). "Nonetheless, we will examine how the efficacies in animal models can be translated to clinical benefits in our planned clinical trials for multiple TSLP-mediated allergic diseases." (PMID 39726595, 2024). "We have summarised the role of basophils and type 2 epithelial cytokines, specifically TSLP and IL‐33, in allergic diseases and helminth infections in humans and mice." (PMID 39654685, 2024). "Histamine, a key mediator of allergic diseases, was reported to upregulate TSLP expression in human keratinocytes and nasal epithelial cells by binding to the histamine H4 receptor, suggesting that histamine can promote TSLP‐dependent atopic disease." (PMID 37165746, 2023). "Further investigations on TSLP will have a better understanding of its biological function on AD and related allergic diseases." (PMID 37096155, 2023). "Studies on humans confirmed the importance of alarmins in IgE-mediated allergies: serum concentrations of TSLP and IL-25 are found to be increased in patients with food allergy, and IL-25 levels appear to correlate positively with atopic severe phenotypes." (PMID 37048784, 2023). "TSLP, along with the epithelium-derived cytokines IL-25 and IL-33, exerts crucial roles in the development of allergic diseases such as atopic dermatitis, food-hypersensitivity and allergic asthma." (PMID 37108740, 2023). "Several studies reported that Astragalus membranaceus inhibited TSLP levels in epithelial cells and a murine model of allergic contact dermatitis and had a therapeutic effect on allergic diseases." (PMID 36673369, 2023). "The TSLP major isoform, known as long-form TSLP (lfTSLP), is upregulated in the airway epithelium of patients with allergic diseases." (PMID 37628907, 2023). "The breakdown of TSLP results initiation of Th2 cytokines, IgE production and Th2-mediated allergic diseases." (PMID 37680747, 2023). "The cytokines TSLP and IL-33 signaling pathways are essential in various inflammatory and allergy reactions." (PMID 36160850, 2022). "A combination of TSLP and allergen stimulates peripheral myeloid dendritic cells of patients with inhalant allergy to induce differentiation of CD4+ T cells into Th2 cells, whereas TSLP alone promotes polarization into Th9 cells." (PMID 35572064, 2022). "As a cardinal cytokine in the pathogenesis of allergic diseases, the cancer-protective effect of TSLP in the lung provides an explanation for the epidemiological observation of an inverse relationship between allergic disease and lung cancer risk." (PMID 35565302, 2022). "Thymic stromal lymphopoietin (TSLP), an IL-7-like cytokine, plays a key role in the development and progression of allergic diseases." (PMID 35409338, 2022). "Thymic stromal lymphopoietin (TSLP), interleukin (IL)-25 and IL-33 are upstream epithelial cytokines and play important roles in allergic diseases." (PMID 35292112, 2022). "Given the importance of TSLP in allergic diseases, the molecular mechanism of TSLP gene regulation has been studied." (PMID 35409338, 2022). "HVE inhibited the release of mediators involved in skin autoimmunity (IL-6 and IL-17C) and allergy (TSLP, IL-6, CCL26, and MMP-9) with a concentration-dependent fashion (IC50s < 25 μg/mL)." (PMID 36012541, 2022). "This represents a large diversity of contexts, with broad physiopathological relevance to bacterial (LPS, HKSA, Curdlan) and fungal (Zymosan) infections, as well as allergy (TSLP)." (PMID 34983927, 2022). "The efficacy of anti-TSLP, anti-IL-33 and anti-IL-25 as monotherapies for treatment of allergic diseases was addressed in a number of studies." (PMID 34084159, 2021).
allergic disease (continued). "This study examined the DNA methylation of the TSLP gene to determine the potential mechanism between phthalate exposure and allergic diseases." (PMID 33836808, 2021). "Thymic stromal lymphopoietin (TSLP), an epithelial cell-derived cytokine, plays a key role in allergic diseases promoted by dendritic cell-mediated T helper cell type-2 (Th2)." (PMID 34443392, 2021). "This is the first study to indicate a potential mechanism between phthalate exposure and childhood allergy in terms of TSLP methylation." (PMID 33836808, 2021). "As TSLP can induce mast cell development and aggravate allergic reactions, putative changes in the mast cells of AEW-treated mice were also investigated." (PMID 34925342, 2021). "Innate cytokines including the alarmins IL-25, IL-33, and TSLP are produced by epithelial cells and are key mediators of allergic disease." (PMID 33717078, 2021). "It was found that in patients with an allergy to shrimp, the concentrations of TSLP and IL-25 in the patients’ blood serum were significantly higher than in the control group." (PMID 34301307, 2021). "The extent to which efficacy can be demonstrated for therapeutics targeting TSLP in allergic diseases remains to be seen when data from current phase 3 trials become available." (PMID 33615121, 2021). "TSLP, which is produced mainly by the lung and gut epithelia, skin keratinocytes, and dendritic cells, is involved in various allergic diseases, including bronchial asthma, atopic dermatitis, and eosinophilic esophagitis." (PMID 33875671, 2021). "Because previous studies have identified TSLP, IL-25 and IL-33 as potent activators of innate lymphoid cells in allergic and non-allergic disease states, we chose to assess potential activation of lung ILC2 by these epithelium-derived cytokines." (PMID 34266437, 2021). "TSLP, IL-33, and IL-25 secreted from HNECs were known as “master switches” in the development of allergic diseases." (PMID 34899052, 2021). "Nasal washes collected from children during confirmed RV infection, have increased thymic stromal lymphopoietin (TSLP) levels at the time of infection which is also linked to atopy and plays a role in many allergic diseases." (PMID 34912343, 2021). "PMA/A23187 acts on mast cells and induces them to produce IL-1β, IL-6, TSLP, and TNF-α, causing allergy-related inflammation." (PMID 34681651, 2021). "Recent identification of memory Th2 cells with high expression of receptors for IL-25, IL-33, and TSLP supports a role of these cytokines in adaptive immune responses in allergy." (PMID 33945508, 2021). "A direct link between TSLP and pathogenesis of allergic diseases including atopic dermatitis, allergic asthma and allergic rhinitis has been reported." (PMID 34305908, 2021). "Cytokine traps targeting IL-33, TSLP, IL-4 and IL-13 are novel tools that nicely complement the use of monoclonal antibodies for the treatment of allergic diseases." (PMID 32754154, 2020). "In support of these observations, it has been published that Notch-deficient keratinocytes fail to differentiate and release high levels of TSLP, which is critical to the development of allergic diseases." (PMID 32012983, 2020). "Biologics targeting upstream cytokines, such as IL-33 and TSLP, are highly anticipated for allergy treatment." (PMID 32066836, 2020). "For instance in allergic disease, epithelial cells can secrete interleukin 25 (IL-25), IL-33, and thymic stromal lymphopoietin (TSLP), which promote proallergenic responses." (PMID 32582164, 2020). "Particularly, in the induction of Th2 inflammation in various allergic diseases, TSLP plays a critical role which is mainly produced by epithelial cells." (PMID 31970850, 2020). "For example, it is well known that EC-derived TSLP promotes OX40L expression on DC to promote Th2 responses, including those underlying allergic disease." (PMID 33154744, 2020).
allergic disease (continued). "The results showed that catechin inhibited the expression of Thymic stromal lymphopoietin (a molecule that plays a main role in the development of allergy) in epithelial cells by influencing the NF-κB/TSLP pathway." (PMID 33202871, 2020). "Thymic stromal lymphopoietin (TSLP) is known for its important role in allergies and atopic dermatitis, and it is up‐regulated in the epidermis of psoriatic patients." (PMID 31556482, 2019). "The JAK/STAT signaling pathway through TSLP/TSLPR has been widely studied for the activation of dendritic cells in allergies/inflammatory diseases such as atopic dermatitis or airway allergies." (PMID 31556482, 2019). "TSLP is widely known to induce Th2 responses by elevating Th2 cytokines such as IL-4, IL-5, and IL-13 in allergic diseases, including AD." (PMID 31817146, 2019). "So far, the operation mode understanding of TSLP signaling pathway has been a difficult problem in the research field of allergic diseases." (PMID 30544712, 2018). "Taken together, these results concurred with reports that suggested a critical role of the epithelium-derived TSLP in allergic reactions and pointed to an important role of IL-12 in the regulation of the epithelium-derived TSLP." (PMID 29896198, 2018). "It is increasingly clear that TSLP, known to be important in allergy, is also critically involved in the control of tumor growth and metastasis, having different effects depending on context, cellular source, and target." (PMID 30214685, 2018). "For example, an allergenic substrate can activate dendritic cells and induce IL-25, TSLP, and allergy-related chemokines." (PMID 30557322, 2018). "ILC2s and many positive regulators including CysLTs, PGD2, IL-33 and TSLP are elevated in the airways of patients with allergic diseases, which supports an environment of ILC2-driven inflammation." (PMID 28959799, 2017). "In particular, we identified key regions near the TSLP locus that likely play a role in regulating TSLP transcription in allergic disease." (PMID 28953906, 2017). "Recently, TSLP has also emerged as an important cytokine in the pathogenesis of non-allergic diseases, including both cutaneous and lung fibrotic conditions of systemic sclerosis and IPF." (PMID 28202030, 2017). "The emergence of TSLP as a central orchestrator of Th2 responses that initiate allergy and inflammation has placed therapeutic targeting of TSLP-mediated signalling against major chronic diseases such as allergic asthma and atopic dermatitis at center stage." (PMID 28368013, 2017). "This shows that innate cytokines, such as TSLP, IL-25, and IL-33, are involved in the development of allergic disease by acting as a link between the innate and adaptive airways." (PMID 28912627, 2017). "The dynamic nature and disease-association of these regions make them strong candidates for regulatory elements that influence TSLP induction in allergic diseases." (PMID 28953906, 2017). "Additional dynamic chromatin regions ~250kb upstream of the TSLP promoter were found to be in high linkage disequilibrium with allergic disease SNPs." (PMID 28953906, 2017). "Previously, it was shown that triclosan, while not sensitizing itself, increased the allergic potential of other allergens and increased asthmatic symptoms in an OVA model of allergy through a TSLP-mediated pathway." (PMID 29124973, 2017). "TSLP expression in the epidermis, epithelium, and submucosa in skin, airway and ocular tissues plays critical role in the pathogenesis of allergic disease." (PMID 27826297, 2016). "Due to its role in priming of naïve CD4+ T cells towards a Th2 response, TSLP has been described to have an essential role in the initiation of allergic diseases." (PMID 27769179, 2016). "A role of TSLP in human allergic diseases is well supported by a variety of mouse models and increased lung tissue expression of TSLP has been detected in mice challenged with dsRNA." (PMID 27399723, 2016).
allergic disease (continued). "TSLP, the signature cytokine of allergic disease, promotes the functions of these same cell types, and is responsible for the extreme itching accompanying atopic dermatitis." (PMID 27431613, 2016). "Higher BPA levels result in increased TSLP, IL-33 and IgE from cord blood, which are biomarkers for allergies and asthma development later in life." (PMID 29051427, 2016). "The role of TSLP has been ascertained in the regulation of various experimental types of allergy, e.g. in models of skin allergy, such as atopic dermatitis or nickel allergy, or in allergic airway diseases." (PMID 26793299, 2015). "Thymic stromal lymphopoietin (TSLP) is involved in the pathogenesis of allergic reactions in the skin and the lung." (PMID 26793299, 2015). "TSLP and IL-33 have recently been recognized for their etiologic role in atopic dermatitis, the earliest manifestation of childhood allergy." (PMID 26084354, 2015). "In a proof-of-concept study, the administration of a fully human anti-TSLP monoclonal antibody G2λ to a small cohort of patients with stable allergic asthma resulted in a significant attenuation of allergy-induced early and late asthmatic responses." (PMID 25889007, 2015). "TSLP in relation to allergy has been first studied in atopic dermatitis where increased levels have been found in inflamed skin associated with Th2-type cytokines." (PMID 26793299, 2015). "Thymic stromal lymphopoietin (TSLP) plays an important role in allergic diseases and is highly expressed in keratinocytes in human lesional atopic dermatitis (AD) skin." (PMID 25866638, 2015). "Itch induced by type 2 mediators such as TSLP, goblet cell hypersecretion of mucus, sneezing, coughing, vomiting, and diarrhea all act as repulsive mechanisms and are particularly common allergy symptoms." (PMID 25101088, 2014). "Studies have demonstrated the role of TSLP in the regulation of Th2 responses in allergic disease from cell different lines." (PMID 24498391, 2014). "In this study, we reported that YPFS significantly inhibited TSLP production in vivo and serum from YPFS-treated mice decreased TSLP production in vitro, which indicated that regulating TSLP is the underlying mechanism of YPFS in reducing allergy relapse." (PMID 25198676, 2014). "Previous reports demonstrated that TSLP plays a critical role in Th2 type allergic inflammation, but the precise roles on the allergic disease remain to be elucidated." (PMID 23437132, 2013). "Another important finding of this study came from the investigation of the role of TSLP during the initiation of Th2 responses vs. established allergic disease." (PMID 23437132, 2013). "Thymic stromal lymphopoietin (TSLP) is an an IL-7-like cytokine which has received considerable attention as a possible “master-switch” in allergic disease." (PMID 23509760, 2013). "IL-25, IL-33 and TSLP, which are produced by epithelial cells, have a shared biological activity to induce Th2 cytokines, suggesting involvement in the development of allergic diseases." (PMID 24205109, 2013). "Our data demonstrate that TSLP enhanced development of Th2 immune responses, but had a little effect on established allergic disease." (PMID 23437132, 2013). "A role for TSLP in allergic diseases was initially attributed to its ability to promote TH2 differentiation through a dendritic cell-mediated pathway." (PMID 22838633, 2012). "Given the role of eosinophil granule proteins in the pathophysiology of allergic diseases, we investigated the ability of TSLP to promote eosinophil degranulation." (PMID 22838633, 2012). "One possible candidate that has been linked to the initiation of inflammatory responses in AD and other allergic diseases is thymic stromal lymphopoietin (TSLP), a member of the hematopoietic cytokine family." (PMID 23284675, 2012). "TSLP is a member of the hematopoietic cytokine family that includes a number of cytokines important in allergic disease including IL-2, IL-4, IL-7, and IL-13." (PMID 22838633, 2012).